VIM (vimentin)
Diseases named in the same sentence as VIM in open-access papers (continued):
Sharing a sentence is not in itself a finding about the gene and the disease.
renal disease (9 papers, 2012 to 2025). "Taken together, these results demonstrate that HNF4A expression is gradually reduced during kidney disease progression, with a parallel gain in VIM expression." (PMID 39954965, 2025). "Vimentin levels increase in Col4a3-/- mice by 5 weeks, and in other renal diseases, but the significance of these changes in expression with disease is not clear." (PMID 27942003, 2016). "VIM is a known marker of epithelial to mesenchymal transition observed in kidney disease." (PMID 41028954, 2025). "Thus, transcription of vimentin may have potential as a kidney disease biomarker at early and potentially reversible stages." (PMID 24475278, 2014). "Similarly, vimentin, a classical marker of mesenchymal cells associated with fibrogenesis, was reduced by losartan treatment, irrespective of the reversal of renal disease." (PMID 22403621, 2012). "Galichon and Hertig came to a similar conclusion, reporting that vimentin is an early and reversible marker of EMT in kidney disease." (PMID 24475278, 2014). "Associated with this protection, we observed the reduced expression of fibrosis-related proteins – such as TGF-β, PAI-1, vimentin and CTGF – which are usually upregulated in renal disorders." (PMID 24742784, 2014).
benign tumors (6 papers, 2014 to 2025). "Among others, CK and vimentin seemed to be more frequently expressed in benign tumors (22.2% versus 5.3% and 76.9% versus 12.5%, respectively)." (PMID 35566714, 2022). "Furthermore, I think that we have solved the puzzle of unexplainable vimentin positivity in benign tumors due to the undiscriminating use of commercially available antibodies recognizing only the full length versus the sliced variant, in addition." (PMID 25798443, 2015).
neurological disease (6 papers, 2010 to 2024). "In brain tissues from several human CNS and non-neurological disease cases, immunoreactivity of vimentin was highly positive in subpial and ependymal cells, but in some white matter astrocytes and in some capillaries, it was weakly positive." (PMID 27875990, 2016). "The level of vimentin in mature astrocytes is variable but, in many neurological disorders, astrocytes undergo several changes showing a reactive phenotype, which is characterized by the increase of vimentin and GFAP expression." (PMID 27120621, 2016). "Recent study has uncovered the important role for VIM and fibrinogen in the progression of numerous neurological diseases, suggesting that these dysregulated peptides might participated in the progression of CSDH." (PMID 38144176, 2023). "On the other side, cotreatment with WSLE and WSLE NE revealed a signification downregulation of APP, GFAP, vimentin, TGF-β, Smad2, and BAX target genes which coincided with previous studies which highlighted the neuroprotective effect of WSLE in a variety of neurological disorders." (PMID 38630361, 2024). "VIM belong to the type III intermediate filament protein, and play an important role in regulates fibrosis, inflammatory response, vascular endothelium, and involvement in neurological diseases." (PMID 38144176, 2023).
inflammation (5 papers, 2014 to 2025). Aberrant reaction of the microcirculation characterized by movement of fluid and leukocytes from the blood into extravascular tissues. "Administration of IV clodronate liposome, known to deplete monocytes, reduced the numbers of alveolar and interstitial macrophages in dually exposed mice, in addition to attenuating lung inflammation and fibrosis, and decreasing levels of MAA, citrulline and vimentin in lung tissues." (PMID 41368636, 2025).
head and neck tumors (4 papers, 2018 to 2025). "Additionally, this analysis revealed that Nano-sar suppressed Src activation and EMT-related proteins, Vimentin and Snail, more efficiently than the free drug in these head and neck tumor xenografts." (PMID 29925404, 2018).
myopathies (4 papers, 2018 to 2025). "Studies have reported increased expression of vimentin in myopathies, indicating that vimentin can serve as a diagnostic marker for dystrophic muscles and myopathies." (PMID 30248895, 2018). "Other proteins of cytoskeleton such as Myosin, Tubulin, Myotilin, Vimentin, Zyxin, Nexilin, and Troponin were found to be differentially expressed in GNE myopathy muscle biopsy samples." (PMID 41339784, 2025).
cardiovascular disease (3 papers, 2012 to 2015). "Nonetheless, our findings add to the growing body of evidence that has suggested a role of vimentin in cardiovascular disease." (PMID 22879973, 2012).
hematologic malignancies (3 papers, 2004 to 2020). "Reactivity with CD45 is diagnostic of a hematopoietic lineage; in addition, apart from vimentin, hematologic malignancies do not generally react with antibodies to other lineage specific markers." (PMID 15550173, 2004).
retinopathy (1 paper, 2019). "Vimentin and NGF expression patterns were often colocalized in the cells of the GCL and in Muller processes across the plexiform layers in OXYS rats at the age of 18 months, suggesting that glial cells accumulate NGF during progressive stages of retinopathy." (PMID 30871541, 2019).
urinary diseases (1 paper, 2025). "In this study, we aimed to develop a non-invasive liquid biopsy assay capable of distinguishing BC from other urinary diseases using a combined Vimentin/POU4F2 methylation panel." (PMID 41029537, 2025).
vasculopathy (1 paper, 2014). "Additional studies are required to clarify the potential role of proteolytic enzymes in degradation of vimentin and other mechanotransduction filaments during the onset of vasculopathy in mLMNA+ mice." (PMID 24661531, 2014). "Data support our view that enhanced expression of vimentin in endothelial cells over the zone of vasculopathy helps to maintain cell viability." (PMID 24661531, 2014). "Defects in mechanotransduction due to defective SMC vimentin may result in the vasculopathy observed in several of the lamin A disorders." (PMID 24661531, 2014).
VIM also shares sentences with these, for which no sentence is quoted: gastrointestinal tumors (7 papers); papillary renal cell carcinoma (5); Ureteral obstruction (5); CNS tumors (4); laryngeal squamous cell carcinoma (4); Renal neoplasm (4); bipolar disorder (3); chromophobe renal cell carcinoma (3); hemangioblastoma (3); nerve sheath tumors (3); neuroendocrine carcinoma (3); pituitary tumor (3); prostate (3); Sjögren’s syndrome (3); Acidosis (2); adenocarcinoma of the gallbladder (2); ankylosing spondylitis (2); benign glioma (2); choroid plexus tumor (2); clear cell sarcoma (2); cystic fibrosis (2); dermatofibrosarcoma protuberans (2); duodenal ulcer (2); fibroxanthoma (2); Glomerular sclerosis (2); hyperplasia (2); Hypertension (2); immune diseases (2); infectious disease (2); lipoleiomyomas (2).
A further 199 diseases each share a sentence with VIM in 2 papers or fewer.